VMA21 (vacuolar ATPase assembly factor VMA21)
Description:
Required for the assembly of the V0 complex of the vacuolar ATPase (V-ATPase) in the endoplasmic reticulum.
Synonyms: MEAX; XMEA
Tractability: Antibody: UniProt predicts a signal peptide or a membrane-spanning region. PROTAC: its protein half-life has been measured.
Gene: Protein-coding gene on chromosome X (151,396,515 to 151,409,364, forward strand). Ensembl gene ENSG00000160131.
Subcellular location: Endoplasmic reticulum membrane; Endoplasmic reticulum-Golgi intermediate compartment membrane; Cytoplasmic vesicle, COPII- coated vesicle membrane
Gene Ontology:
Molecular function: protein binding
Biological process: lysosomal lumen acidification; vacuolar proton-transporting V-type ATPase complex assembly
Cellular component: endoplasmic reticulum membrane; endoplasmic reticulum-Golgi intermediate compartment membrane; lysosome; ER to Golgi transport vesicle membrane
Homologues: Orthologues: macaque VMA21 (100% identical), mouse Vma21 (94% identical), chimpanzee VMA21 (86% identical), guinea pig VMA21 (86% identical), rat Vma21 (82% identical), dog VMA21 (81% identical), tropical clawed frog vma21 (78% identical), zebrafish vma21 (70% identical), Caenorhabditis elegans R07E5.19 (27% identical), Drosophila melanogaster CG5969 (23% identical), Caenorhabditis elegans R07E5.7 (21% identical), Drosophila melanogaster CG42359 (20% identical).
Diseases named in the same sentence as VMA21 in open-access papers:
VMA21 is named in the same sentence as 29 diseases in open-access papers, as found by Europe PMC text mining. Sharing a sentence is not in itself a finding about the gene and the disease. The quoted sentences say what the papers report.
lung adenocarcinoma (5 papers, 2020 to 2025). A carcinoma that arises from the lung and is characterized by the presence of malignant glandular epithelial cells. "This rise in VMA21 is associated with the promotion of lung adenocarcinoma growth." (PMID 40332167, 2025). "Diverse mechanisms by which ZFPM2-AS1 modulates cancer progression have been well revealed, including stabilizing MIF in gastric cancer and sponging miR-18b-5p to regulate VMA21 expression in lung adenocarcinoma." (PMID 32065218, 2020). "In addition, the upregulation of miR-18a-5p enhances the ability of lung adenocarcinoma cells to proliferate via the miR-18b-5p/VMA21 axis." (PMID 33428596, 2021). "According to findings from a study on lung adenocarcinoma, the ZFPM2-AS1 molecule was shown to lower the levels of miR-18b-5p, which subsequently leads to an increase in VMA21 levels." (PMID 40332167, 2025).
X-linked myopathy with excessive autophagy (5 papers, 2016 to 2026). X-linked myopathy with excessive autophagy is a childhood-onset X-linked myopathy characterized by slow progression of muscle weakness and unique histopathological findings. "X-linked myopathy with excessive autophagy (XMEA), a rare childhood-onset autophagic vacuolar myopathy caused by mutations in VMA21, is characterized by proximal muscle weakness and progressive vacuolation." (PMID 39994482, 2025). "X-linked myopathy with excessive autophagy (XMEA) is a slowly progressive disease affecting male patients, caused by hemizygous mutations in the VMA21 gene." (PMID 41307411, 2026). "X-linked myopathy with excessive autophagy (XMEA) is a rare neuromuscular disorder caused by mutations in the VMA21 gene, encoding a chaperone protein present in the endoplasmic reticulum (ER)." (PMID 40033998, 2025). "X-linked Myopathy with Excessive Autophagy (XMEA) is a rare autophagic vacuolar myopathy caused by mutations in the Vacuolar ATPase assembly factor VMA21 gene; onset usually occurs during childhood and rarely occurs during adulthood." (PMID 36553512, 2022).
ovarian carcinoma (4 papers, 2020 to 2025). A malignant neoplasm originating from the surface ovarian epithelium. "A related study has found that diminished levels of miR-18b-5p in ovarian cancer cells target VMA21, thereby inhibiting both proliferation and metastasis." (PMID 40332167, 2025). "Another research demonstrated that lncRNA LOXL1-AS1 affected ovarian cancer cell growth, migratory, and invasion by modulating the miR-18b-5p/VMA21 axis." (PMID 33381389, 2020). "Also, LOXL1-AS1 can bind to miR-18b-5p and miR-18b-5p targets Vacuolar ATPase Assembly Factor (VMA21) in ovarian cancer." (PMID 39136001, 2024). "However, the recent evidence also shows that VMA21 may have a positive role to promote the growth of ovarian cancer and lung cancer cells." (PMID 33680927, 2020).
cervical cancer (2 papers, 2020 to 2021). A primary or metastatic malignant neoplasm involving the cervix. "VMA21 has been documented to be negatively regulated by miR-18b-5p, which was involved in the progression of LUAD and cervical cancer." (PMID 34507559, 2021).
lung carcinoma (2 papers, 2020 to 2023). "circ_0001361 accelerated cell proliferation and metastasis of lung cancer by sponge miR-525-5p to upregulate VMA21 expression." (PMID 37588107, 2023).
metabolic syndrome (2 papers, 2015 to 2022). A cluster of metabolic risk factors for CARDIOVASCULAR DISEASES and TYPE 2 DIABETES MELLITUS. "Deficiency in VMA21 results in impaired autophagy and endoplasmic reticulum stress and is associated with development of metabolic syndrome." (PMID 26258540, 2015).
colon cancer (1 paper, 2020). "Overexpression of VMA21 in human colon cancer LoVo and SW620 cells significantly suppressed colony formation ability." (PMID 33680927, 2020).
congenital disorder of glycosylation (1 paper, 2025). Congenital disorder of glycosylation (CDG) is a fast growing group of inborn errors of metabolism characterized by defective activity of enzymes that participate in glycosylation (modification of proteins and other macromolecules by adding and processing of oligosaccharide side chains). "Recent years have witnessed a surge of interest in VMA21, with the identification of novel mutations causing a congenital disorder of glycosylation (CDG) with liver affection, and its potent implication in cancer predisposition." (PMID 40033998, 2025).
disc degeneration (1 paper, 2023). "Furthermore, the injection of human adenovirus circ-VMA21 into punctured IVDs attenuates degenerative changes in the NP and reduces disc degeneration in a rat model of IVDD." (PMID 38192334, 2023).
follicular lymphoma (1 paper, 2022). Follicular lymphoma is a form of non-Hodgkin lymphoma characterized by a proliferation of B cells whose nodular structure of follicular architecture is preserved. "Here, we demonstrate novel results that help in understanding the role of the follicular lymphoma-associated hotspot mutation VMA21p.93X, which corresponds to Vma21[Δ66-77] in S. cerevisiae cells." (PMID 37389034, 2022).
hyperlipidemia (1 paper, 2022). "Compared with VMA21 deficiency (25% increase in LDL-c) and ATP6AP2 deficiency (on average 20% increase in LDL-c), the hyperlipidemia in TMEM199 and CCDC115 deficiency clearly was more pronounced (124% increase in LDL-c)." (PMID 34626841, 2022).
lymphoma (1 paper, 2022). A malignant (clonal) proliferation of B- lymphocytes or T- lymphocytes which involves the lymph nodes, bone marrow and/or extranodal sites. "Therefore, in the previous study, the VMA21p.93X mutation was created by transfecting the plasmid containing the mutated VMA21 cDNA into WT lymphoma cells and the 293T cell line." (PMID 37389034, 2022).
melanoma (1 paper, 2023). A malignant, usually aggressive tumor composed of atypical, neoplastic melanocytes. "By regulating the miR-224-5p/VMA21 axis, LINC00665 promotes melanoma cell growth and migration." (PMID 37229449, 2023).
cancer (6 papers, 2020 to 2025). A tumor composed of atypical neoplastic, often pleomorphic cells that invade other tissues. "In this study, we identified VMA21 as the only candidate gene showing differential expression between cancer and noncancerous colorectal tissues among five known assembly factor genes (TMEM199, VMA21, CCDC115, ATP6AP1, and ATP6AP2) of the V0 domain." (PMID 33680927, 2020). "In this study, the expression of VMA21 was correlated with the expression of ATP6AP1 and ATP6AP2, although which were not differentially expressed between cancer and noncancer tissues." (PMID 33680927, 2020).
myopathy (4 papers, 2020 to 2024). A disease of the muscle in which the muscle fibers do not function properly. "For instance, germline mutations in the V-ATPase chaperone VMA21 cause a specific myopathy in humans but spare most other cell types." (PMID 34652942, 2021). "Lesions in VMA21 that disrupt v-ATPase assembly have also been shown to cause myopathies." (PMID 34311841, 2021). "Irrespective of the mutations detected so far, myopathy is the exclusive manifestation of VMA21 mutation carriers, and since VMA21 is located on the X-chromosome, it occurs only in males (X-linked myopathy with excessive autophagy (XMEA))." (PMID 32316520, 2020).
tumor (3 papers, 2020 to 2022). "Previous investigation of the underlying molecular mechanism showed that VMA21 deficiency decreases lysosomal-mediated degradation and blocks autophagy, and increased autophagy inhibits tumor progression." (PMID 33680927, 2020). "Recently, we reported that a somatic VMA21 hotspot mutation identified in tumor samples from FL patients, VMA21 p.93X, results in a partial defect in lysosomal acidification and proteolytic activity, along with elevated autophagy even though MTOR remains active." (PMID 37389034, 2022). "Collectively, depletion of circ_0001361 suppressed xenograft tumor growth via regulating miR-525-5p/VMA21 axis." (PMID 34507559, 2021). "The present data suggest that VMA21 acts as a tumor suppressor and predicts a favorable prognosis, although VMA21 expression is elevated in CRC tissues." (PMID 33680927, 2020). "The effects of variations in the expression of VMA21 on tumor growth were assessed in vitro and in vivo." (PMID 33680927, 2020). "Finally, inhibition of circ_0001361 restrained in vivo xenograft tumor growth via regulating miR-525-5p/VMA21 axis." (PMID 34507559, 2021). "Additionally, miR-525-5p-mediated anti-tumor effects were counteracted by VMA21 overexpression in LUAD cells." (PMID 34507559, 2021). "Besides, the mRNA and protein levels of VMA21 in tumor tissues were evidently reduced by silencing of circ_0001361." (PMID 34507559, 2021). "In addition, the levels of circ_0001361, miR-525-5p, and VMA21 in tumor tissues were determined." (PMID 34507559, 2021). "Finally, the potential mechanism about the role VMA21 as a tumor suppressor was not explored in the present study." (PMID 33680927, 2020). "Therefore, high VMA21 expression suppresses tumor growth in vivo, indicating that VMA21 is a negative regulator of CRC tumorigenicity." (PMID 33680927, 2020).
VMA21 also shares sentences with these, for which no sentence is quoted: gastric cancer (2 papers); infection (2); adenoma (1); breast tumors (1); deafness (1); genetic disease (1); glioma (1); Insulin resistance (1); liver disease (1); metabolic myopathy (1); psychosis (1); renal cell cancer (1); renal tubular acidosis (1).